CD8B (CD8 subunit beta)
Diseases named in the same sentence as CD8B in open-access papers (continued):
Sharing a sentence is not in itself a finding about the gene and the disease.
ovarian carcinoma (2 papers, 2015 to 2022). A malignant neoplasm originating from the surface ovarian epithelium. "Except for CD8B, TRAT1 and SYK, all the other module genes were found to be significantly associated with survival of ovarian cancer patients (p < 0.05)." (PMID 26099452, 2015).
co-infection (1 paper, 2023). "After co-infection, the main CD8β cytokine producers were TNF+IFN-γ+, which peaked at 28 dpi." (PMID 37287962, 2023). "However, PRRSV-2/H3N2 co-infection decreased the magnitude of CD8β+ T-cell responses (mean of 5.56% and 2.97% between single-infected and co-infected groups, respectively)." (PMID 37287962, 2023). "In BALCs, the patterns of cytokine production by CD4+ and CD8β+ T cells differed between single H3N2 infection and PRRSV-2/H3N2 co-infection." (PMID 37287962, 2023). "Similarly, after co-infection, the H3N2-specific CD8β+ IFN-γ T-cell response dominated and peaked at 14 dpi, with a higher frequency (0.23%) in comparison to the H3N2 single infection." (PMID 37287962, 2023). "High frequencies of PRRSV-2-specific CD8β+ T cells expressing TNF were observed in PRRSV-2 single-infected and PRRSV-2/H3N2 co-infection groups (64.50% vs. 45.05%, respectively), followed by double TNF/IL-2 (6.39% vs. 29.05%, respectively) and TNF/IFN-γ (28.96% vs. 25.63%, respectively) producers." (PMID 37287962, 2023). "In Exp 2, H3N2-specific CD4+ and CD8β+ T-cell responses in BALCs were also higher but not significantly so after PRRSV-2/H3N2 co-infection (mean of 1.71% vs. 0.90% within CD4+ T cells and 0.54% vs. 0.36% within CD8β+ T cells)." (PMID 37287962, 2023).
colon cancers (1 paper, 2024). "In this study, the average expressions of CD8A, CD8B, GZMA, GZMB, and PRF1 genes were used to represent level of CTL in colon cancers." (PMID 38327746, 2024).
colorectal cancer (1 paper, 2010). A primary or metastatic malignant neoplasm that affects the colon or rectum. "Although the function of CD8β chain is not well defined, we included this protein in the analysis as it has a role in chromatin modifications and alterations in its consensus coding sequences have been found in human breast and colorectal cancers (Sjöblom, 2006)." (PMID 20424609, 2010).
COVID-19 (1 paper, 2022). A disease caused by infection with severe acute respiratory syndrome coronavirus 2. "Though both unexposed and COVID-19 patients responded consistently to CMV and PHA, they did not respond to CD8-A and CD8-B MPs substantially." (PMID 36248882, 2022).
esophageal adenocarcinoma (1 paper, 2023). A malignant tumor with glandular differentiation arising predominantly from Barrett mucosa in the lower third of the esophagus. "Significant lower infiltration of CD8 T cells and M1 macrophages and a lower expression of CD8A, CD8B, and TBX21 were found also in Esophageal Adenocarcinoma TCGA panCancer Atlas in the normal tissue of patients with nodal metastasis." (PMID 36281585, 2023).
foot and mouth disease (1 paper, 2025). A viral infectious disease that results in infection in cattle and swine, has material basis in foot-and-mouth disease virus, which is transmitted by contaminated fomites, or transmitted by ingestion of food contaminated with infected meat or animal products. "It has been speculated that the CD4+/CD8b+ T cell population may be an uncharacterized population of peripheral T helper cells, as an increase in CD4+/CD8+ T cells was observed in accordance with B cell proliferation following vaccination for foot and mouth disease in cattle." (PMID 40316897, 2025).
Hypertension (1 paper, 2022). The presence of chronic increased pressure in the systemic arterial system. "Depleting CD8+ T cells using anti-CD8β antibodies greatly attenuated cardiac fibrosis in three different hypertensive mouse models indicating that it affects fibrosis independently of hypertension etiology." (PMID 36483558, 2022).
influenza (1 paper, 2018). An acute viral infection of the respiratory tract, occurring in isolated cases, in epidemics, or in pandemics; it is caused by serologically different strains of viruses (influenzaviruses) designated A, B, and C, has a 3-day incubation period, and usually lasts for 3 to 10 days. "Using a non-assumptive approach of overlapping peptides spanning the whole protein sequence of PR8 strain NP, we generated influenza-specific CD8β+ T-cell lines and defined four new SwIV epitopes in the Babraham pigs." (PMID 29772011, 2018). "Successful establishment of conditions for pig T-cell culture enabled us to define influenza-derived, immunodominant CD8β+ cytotoxic T-cell epitopes in the Babraham pig." (PMID 29772011, 2018).
parasitemia (1 paper, 2019). "Depletion of CD8+ T cells with antibodies to CD8α or CD8β increased parasitemia in PyNL infection, with ~50% mortality." (PMID 31608052, 2019).
Parkinson disease (1 paper, 2024). A progressive degenerative disorder of the central nervous system characterized by loss of dopamine producing neurons in the substantia nigra and the presence of Lewy bodies in the substantia nigra and locus coeruleus. "CD8 subunit beta gene (CD8B) is a cytotoxic T cell marker, which was previously found to be increased in colon tissues of Parkinson’s disease patients in a study in which immune overlap with IBD was examined." (PMID 38931955, 2024).
renal cell carcinoma (1 paper, 2022). "In the renal cell carcinoma case, “small nests” of tumors showed a higher density of CD8A, CD8B, and CD4 expression than “large nests,” and these transcript levels were even higher in regions of desmoplasia surrounding vessels." (PMID 35584630, 2022).
Stroke (1 paper, 2024). Sudden impairment of blood flow to a part of the brain due to occlusion or rupture of an artery to the brain. "Our findings further support the inverse association between CD45RA on naive CD4+ cells and CD8 on CM CD8b with stroke occurrence." (PMID 38894965, 2024).
thymoma (1 paper, 2013). A neoplasm arising from the epithelial cells of the thymus. "Lentiviral vectors expressing M-1 or M-4 isoform were transduced into the JM thymoma cells (CD4+, CD8α+, CD8β−) to generate stable cell lines that differed only in the expression of each CD8β isoform." (PMID 23533620, 2013).
tumor (122 papers, 2013 to 2026). "Accordingly, expression of genes encoding IFNγ, CD8α and CD8β was significantly increased in tumor samples with a low TSP1 expression." (PMID 34439212, 2021). "We observed the following hierarchy in immune response in tumor-bearing mice: the CD8 T cell response was superior in CD8β-depleted mice and equivalent in pfn-deficient and SV40LgT and GFP-tolerant mice." (PMID 25101081, 2014). "Furthermore, mRNA expression studies, demonstrate a negative correlation between DVL-1 expression and the markers for T cell exhaustion (e.g. CTLA4, HAVCR2), CD8+ T cell (CD8B), tumor-associated macrophages (TAM), T helper cell, and dendritic cells." (PMID 34659647, 2021). "After 4 days of co-culture of splenocytes with DC lines, we observed a CD8+ T cell response that was markedly higher in splenocytes from the C57BL/6, CD4-depleted, and FasL-deficient mice than in splenocytes from the tumor-bearing CD8β-depleted, Pfn-deficient, and CD11c:SV40LgT hosts." (PMID 25101081, 2014). "The model including CD8β+, the BMI, neutrophile/lymphocyte ratio and tumor location had an AUC of 0.67 (95% CI 0.62-0.72)." (PMID 41749825, 2026). "We further confirmed the anti-tumor memory response by using an anti-CD8β antibody to deplete CD8 T-cells before tumor rechallenge." (PMID 41048107, 2025). "In bilateral MC38 tumor-bearing mice, it was shown that CD8 T-cell depletion with an anti-CD8β mAb completely abolished 17D-induced tumor delay in those directly injected and in the contralateral tumor nodules, leading to reduced overall survival." (PMID 39852819, 2025). "Collectively, these results demonstrate that RaST recruited a higher number of CD11b+ and CD11c+ tumor-infiltrating immune cells than the marginal CD8b+ cells, indicating the dominance of innate than adaptive immune response." (PMID 38558990, 2024). "PLA2G2D, IFNG, CD8B and NKG7 were found to be significantly upregulated, which are associated with tumor immunity." (PMID 35530341, 2022). "Treatment with anti-CD8β depleting mAb resulted in tumor re-growth in 2/2 mice (p < 0.01 of combined depletion data versus control)." (PMID 35013519, 2022). "We defined several immune subsets from the spleen and tumor by using CD8b, Thy1.1, PD-1, NK1.1, CD11b, CD11c, MHC-II, CD80, Ly6G, Ly6C, F4/80, and CD206 antibodies." (PMID 36497152, 2022). "Patients that respond to PD-1 blockade also exhibited increased expression of STAT1, CXCL9, CXCL10, GZMB, CD8A, and CD8B, which is consistent with our observation in tumor model with IFNα-MSC treatment." (PMID 35145233, 2022). "The 63 upregulated genes, including PLA2G2D, IFNG, LAG3, CD8B and NKG7, were associated with tumor immunity." (PMID 35530341, 2022). "Given the overall TME scores of LUAD and LUSC patients, B cell, DC1, and six hub genes, like CD8A, CD8B, and PD-L1, were significantly positively correlated with stromal score and immune score and significantly negatively correlated with tumor purity." (PMID 34422829, 2021). "CD8β antibody-depletion allowed both tumour establishment in naïve mice, and the progressive growth of SCC following tacrolimus removal in our rejection model, highlighting a critical role for CD8+ T cells in the control of SCC." (PMID 33925140, 2021). "Depletion of CD8β+ T cells or TCRβ+ T cells resulted in an inability to reject established SCC tumours." (PMID 33925140, 2021). "In our previous work, RNA levels of CD8A and CD8B (markers of cytolytic T cells) in tumors from patients prior to initiating BRAFi therapy demonstrated a positive correlation with eventual tumor regression after treatment." (PMID 32528881, 2020). "In contrast, up-regulation of Cd8b, Ifng and Il18 with combination treatment was highest at d28, coinciding with tumor regression." (PMID 31921384, 2019). "By contrast, a perforin+CD8β+ T-cell population was clearly detected in the tumor with nearly a threefold increase compared with peripheral blood; indicating a cytotoxic infiltration to the tumor." (PMID 29930558, 2018).
tumor (continued). "Using depleting anti-CD8β antibodies, we were able to induce efficient tumor growth in C57BL/6 mice." (PMID 25101081, 2014). "Additionally, moderate increases in HLA class–CD8B interactions suggested enhanced tumor antigen presentation and activation of cytotoxic T cell responses." (PMID 40941002, 2025). "Next, we assessed whether the increased T cell recruitment was necessary for tumor inhibition by depleting CD8 + T cells using CD8β-depleting antibodies." (PMID 40796746, 2025). "This trend was consistent when the tumor tissues were stratified by CD8A or CD8B expression." (PMID 39679910, 2025). "The immune response against tumor induced within OCM skeletal muscle was previously characterized as an intratumoral infiltration of cytolytic CD8β+ T cells, which may be what was observed in the present study." (PMID 36579622, 2023). "CD8α, produced from CD8A, is a canonical marker for the T cell population involved in tumour surveillance and forms a heterodimer with CD8β, or may homodimerise; CD8A is the only gene exclusive to T-net that correlates with nivolumab response in MEL_PROG." (PMID 35743743, 2022). "Our data demonstrated that GPX8 was correlated with mRNA expression of immune markers of CD8+ T cells (CD8B), CD4+ T cells (CD4), T cells (CD3D), macrophages (CD68 and ARG1), neutrophils (ITGAM and CCR7), dendritic cells (NRP1), NK cells (B3GAT1), and tumor-associated fibroblasts (FAP)." (PMID 36061208, 2022). "Similarly, high DC1 LUSC and normal tissues had higher CD8A and CD8B expression than low DC1 infiltration tumor samples." (PMID 34422829, 2021). "Depletion of CD8β+ T cells or TCRβ+ T cells was sufficient to permit SCC tumour establishment." (PMID 33925140, 2021). "We found a significantly diminished expression of CD8B mRNA in tumours overexpressing mutant forms of the EGFR, confirming the described effect of the mutated EGFR expression on reducing the CD8 T-cell infiltration in these tumours." (PMID 35052732, 2021). "Therefore, we restricted our analysis on CD8B gene expression as a specific marker for CD8 T-cells and quantified the relative abundance of CD8 T-cells in LUAD tumours with EGFR oncogenic mutations compared to EGFR wild-type (Wt) LUADs." (PMID 35052732, 2021). "We obtained results on the correlation between TPPP3 expression and marker genes of tumor infiltration-associated immune cells, including CD8+T cells (CD8A and CD8B), B cell (CD19 and CD79a), and Myeloid dendritic cell (HLA-DPB1, HLA-DQB1, HLA-DRA, HLA-DPA1, CD1C, NRP1, and ITGAX)." (PMID 33083464, 2020). "Furthermore, antigen-presenting molecules and immune molecular interactions, such as those between HLA-A, HLA-B, HLA-C, HLA-E, and HLA-F with CD8A and CD8B, appeared to be significantly up-regulated in tumor tissues, while their presence in normal tissues was comparatively diminished." (PMID 40723292, 2025). "Interestingly, a slow-down in tumour growth and improved survival was apparent when ‘Anti-CD8β + Anti-Gr-1’ was compared to CD8β+-depletion alone, and two out of eight animals could reject established SCC tumours." (PMID 33925140, 2021). "In the TME, CD8+ (CD8a+CD8b+) T cells are known to be differentiated from lymphocyte T cells (CD45+, CD3e+), and that has a key role in anti-tumor immunity." (PMID 39682244, 2024). "CD8B/FOXP3 expression ratio and intra-tumor CD8+ T cell density were positively correlated, indicating consistency between transcriptomic and proteomic data." (PMID 39013886, 2024). "To validate the involvement of CD8+ T cells in the tumor-promoting role of ID1 expressing TAMs, we depleted CD8+ T cells using systemic administration of an anti-CD8β antibody in a CT26 s.c. model." (PMID 37996458, 2023). "After adjusting for tumour purity, there was a correlation between CD44 outside CD8B and NOS2 and most of the immune markers." (PMID 36316684, 2022).
tumor (continued). "With correlating gene expression profiles of cytotoxic T lymphocyte (CTL) markers (CD8A, CD8B, GZMA, GZMB, and PRF1) with T-cell characteristics, the TIDE algorithm predicts immunotherapy of tumor patients." (PMID 36618968, 2022). "Based on the TIMER2.0, we found that six hub genes were significantly related to CD8A, CD8B, and PD-L1 in the LUAD and LUSC and most other tumor tissues in TCGA." (PMID 34422829, 2021). "T and tumor cells were identified by the expression of classic cell type markers, including PTPRC, CD3G, CD3E, TRBC1, and CD8B for T cells and MAGEA 4 for MEL-526 cells." (PMID 33754038, 2021). "In our study, LTA was positively correlated with CD8+ T-cell infiltration and its markers’ expression after adjusting by tumor purity, such as CD8A, CD8B, and IL2RA." (PMID 35155447, 2021). "Furthermore, our results suggested that a low ratio of PD-L1 mRNA/CD8B mRNA in tumor tissues after definitive CRT could be a potential prognostic maker for salvage surgery, although the clonal expansion of TIL itself was not enough to improve the prognosis there." (PMID 33499345, 2021). "The infiltration of anti-tumor effector cells i.e., CD8+ T cells was analyzed using CD8A and CD8B as gene markers." (PMID 33276627, 2020). "For instance, elevated expression of CD8B gene and its pseudogene CD8BP in HPV16+ HNSC tumours compared with HPV− tumours can indicate increased lymphocyte infiltration of the HPV16+ tumour." (PMID 29263803, 2016). "In order to be able to transfer the large T expressing tumor cells into immunocompetent mice, host CD8+ T cells were depleted with an anti-CD8β antibody before adoptive transfer." (PMID 26247358, 2015). "Moreover, our spatial transcriptomic analysis demonstrates that in LIHC tumour tissues, GMIP spatially overlaps significantly with the CD8+ T cell markers CD8A and CD8B." (PMID 40275529, 2025). "To determine whether the delay in resistance mediated by ECM inhibition was CD8+ T cell–dependent, we treated YUMM1.7 tumor‐bearing mice with DHB and concurrently depleted CD8+ T cells using an anti‐CD8b antibody." (PMID 40847444, 2025). "Notably, the enhanced cytotoxic activity (CD8A, CD8B, and NFKB1) observed in irradiated T cells suggests a potential mechanism contributing to the improved tumor control observed in our study." (PMID 39445067, 2024). "Immune-related genes, such as CD8A, CD8B, GZMA, GZMB, and PRF1, that may indicate the function of tumor-infiltrating CD8 + T cells were considerably enriched in the group receiving combination therapy." (PMID 37777634, 2023). "Among them, the expression levels of CD8A, CD8B, GZMA, GZMB, and PRF1 were used to evaluate the infiltration levels of tumor cytotoxic T lymphocytes (CTLs), and a high-CTL-infiltration group has been related to significantly prolonged survival time of patients receiving immunotherapy." (PMID 36405701, 2022). "Likewise, most ICD-related genes, including IL-6, IL-10, NLRP3, CD8A, CD8B, and TLR4, exhibited attenuated expression levels in tumor cells compared to normal cells." (PMID 36225939, 2022). "Introduction of CD8β did not further enhance tumor recognition but was functionally involved in the molecular interaction with its target when present." (PMID 34759930, 2021). "Tumours grew progressively in mice lacking either CD8β+ T cells or TCRβ+ T cells, resulting in reduced survival." (PMID 33925140, 2021). "Moreover, CD163 expression was positively correlated with most gene markers of these tumor-infiltrating immune cells in both the TCGA and CGGA cohorts, including CD8A, CD8B, STAT6, STAT5A, and PDCD1." (PMID 34395626, 2021). "MC38 tumor-bearing mice were treated with an anti-CD8β antibody on day 4, which depletes CD8+ T cells, but not CD8α-expressing dendritic cells." (PMID 32273499, 2020).